ADAM17 (ADAM metallopeptidase domain 17)
Diseases named in the same sentence as ADAM17 in open-access papers (continued):
Sharing a sentence is not in itself a finding about the gene and the disease.
tumor (continued). "The FERM domain protein iTAP/Frmd8, which binds to and stabilizes the ADAM17/iRhom sheddase complex at the cell surface, is a regulator of inflammation, epithelial homeostasis, and tumor growth in vivo." (PMID 36720499, 2023). "To determine the putative contribution of ADAM17 to the release of endogenous ephrin-A1 from the cell surface of tumor cells, we analyzed the supernatant of ADAM17 inhibited cells (TMI-005 or MEDI3622 treated) and compared it to their untreated controls." (PMID 36998455, 2023). "ADAM17 was shown to be positively correlated with immune cell infiltration and immune checkpoint expression via the Tumour Immune Estimation Resource (TIMER) database and immunohistochemistry analyses." (PMID 38069391, 2023). "PPI network analysis using STRING indicated that ADAM17 plays an important role in tumour progression and immune evasion." (PMID 38069391, 2023). "We recently have shown that IR enhances ADAM17 activity in NSCLC cell lines which contributes not only to the radioprotection of the tumor itself, but also its vasculature." (PMID 36998455, 2023). "(D) Heatmaps showing expression of ICAM1 and ICAM-1 cleavage related proteases MMP9, ELANE, CTSG, ADAM10, and ADAM17 in normal or tumor tissue of 22 different cancer types." (PMID 37732732, 2023). "ADAM17 can serve as a signaling scissor in the tumor microenvironment, enabling cancer cells to enhance their resistance to their surroundings." (PMID 37175410, 2023). "In this work, we decided to determine the involvement of NOX1 and ADAM17 in the generation of sMCAM from blood vascular endothelial and cancer cells and to demonstrate its contribution to tumor angiogenesis and cancer progression." (PMID 38137406, 2023). "Here, we investigate IR-induced tumor cell motility and link it mechanistically to an IR-enhanced ADAM17-EphA2 signaling network acting on an auto- and paracrine level." (PMID 36998455, 2023). "This indicates that ADAM17 and its shed ligands are driving forces for the directed, IR-induced tumor cell migration." (PMID 36998455, 2023). "In contrast to their previous study, they found that miR-145 is downregulated in HCC and is considered as a tumor suppressor activated via ADAM17." (PMID 37185715, 2023). "Collectively, these results show that the inactivation of ADAM17 results in the suppression of tumour growth, inhibition of cellular proliferation and increased apoptosis in FGFR2‐mutant ECs." (PMID 37165578, 2023). "The results showed that ADAM17 knockdown significantly suppressed the increase in tumour volume and weight." (PMID 38069391, 2023). "To investigate a putative signaling link between EphA2 and ADAM17-mediated tumor cell migration, we first determined the phosphorylation status of EphA2 S897 after pharmaceutical inhibition of ADAM17 activity." (PMID 36998455, 2023). "CRC cells advance as ADAM10 and ADAM17 cleave mMICA or membrane-bound IL-6R in the tumor microenvironment, and furthermore, the shedding of membrane-bound L1-CAM influences metastasis." (PMID 36572816, 2023). "Chemotherapeutic agents can activate ADAM17, leading to the cleavage of its substrates and acceleration of tumor growth." (PMID 37175410, 2023). "We next evaluated the in vivo antitumor efficacy of ADAM17 inhibition in a murine xenograft tumour model." (PMID 37165578, 2023). "In this study, using TCGA and GTEx datasets, we examined the high expression levels of ADAM17 in various tumours, particularly those in HCC tissues, and verified these results using IHC." (PMID 38069391, 2023). "The level of soluble ephrin-A1 was strongly reduced in NCI-H358 and PC-3 tumor cells treated with the ADAM17 inhibitor." (PMID 36998455, 2023). "Mice bearing subcutaneous tumors were photographed at the end of the experiment to compare the effects of ADAM17 knockdown on tumor size." (PMID 37175410, 2023). "Inhibition of ADAM17 expression by siRNA can increase the sensitivity of A549 cells to anti-tumor drugs; ADAM10 was overexpressed in A549 cells." (PMID 36606198, 2022).
tumor (continued). "ADAM17 regulates signal transduction in many pathophysiological processes, including inflammation, immunity and tumor." (PMID 36466812, 2022). "In this article, we summarized the structure and multiple regulatory roles of ADAM17, the latest immune regulation of ADAM17 in tumor formation and development, as well as the progress in the development of ADAM17 inhibitors." (PMID 36466812, 2022). "ADAM17 is expressed in all normal tissues and upregulated in some tumor tissues, suggesting that all the organs can be potentially infected." (PMID 35720350, 2022). "L1CAM can also be cleaved by the metalloproteinases, ADAM10 and ADAM17, which further results in the release of a 200 kDa soluble ectodomain fulfilling diverse functions in both tumor and immune cells." (PMID 35473609, 2022). "In order to reveal if the expression of these miRs also negatively correlates with ADAM10 and ADAM17 expression patterns in primary RBs, 15 RB patients’ tumor samples were analyzed." (PMID 36293469, 2022). "Other studies on the role of ADAM17 in CRC have shown that ADAM17 cellular levels can increase the mobility of cancer cells and the expression of proangiogenic factors that can determine tumor progression and metastasis." (PMID 36286024, 2022). "Some of these, including ADAM9, ADAM10, ADAM12, ADAM15, and ADAM17, are shown to be upregulated in both tumor tissues and cancer cell lines, and their expression correlates to adverse patient survival and/or treatment response." (PMID 35998057, 2022). "It was recently shown that ADAM17-mediated shedding of the TNF-receptor 1 (TNFR1) is the initiating event of TNFα-induced necroptosis in endothelial cells promoting tumor cell extravasation and metastasis formation." (PMID 35892600, 2022). "The protein concentration of ADAM17 in tumor tissue (0.28 vs. 0.20 ng/μg protein, p = 0.01) and in the surgical margin (0.22 vs. 0.16 ng/μg protein, p < 0.05) of diabetic patients was higher than in non-diabetic patients." (PMID 36286024, 2022). "CD16a is a hot topic discussed in recent NK cell anti-tumor immunity, and more information about the role of ADAM17 in the regulation of CD16a in NK cells can be seen in some recent studies." (PMID 36466812, 2022). "It was found that ADAM17 was significantly higher in multiple human tumor tissues than in adjacent tissues, and that cancer patients with high ADAM17 expression had a poor clinical prognosis." (PMID 36558177, 2022). "The mean protein concentration of ADAM17 for the study group was higher in the tumor than in the margin tissue (0,23 vs. 0.18 ng/μg protein, p = 0.09), but the results were not statistically significant." (PMID 36286024, 2022). "ADAM17 immunostaining was mainly localized in the tumor cell cytoplasm and was detected in most samples, with variable intensity across the cohort." (PMID 36140519, 2022). "ADAM17 is usually expressed in various malignant tumors, while rarely expressed in normal cells, implying its specificity in the tumor." (PMID 35720350, 2022). "Beyond vascular endothelial cells, ADAM17 is also important in lymphatic endothelial cell-induced tumor migration and metastasis." (PMID 36466812, 2022). "In summary, our analysis uncovered that ADAM17 is expressed in both normal (especially in the lung) and tumor tissues and is highly expressed in several tumor samples." (PMID 35720350, 2022). "ADAM17 immunostaining was detected in most samples, mainly localized in the tumor cells, with variable intensity across the cohort." (PMID 36140519, 2022). "Deletion of ADAM17 gene inhibited tumor growth, increased the survival in tumor-bearing mouse models, and resulted in a significant decrease in CD163+ cell population." (PMID 36466812, 2022). "Eight drugs were targeted only for ADAM17, demonstrating the immune implications of targeting ADAM17 to prevent tumor progression and SARS-CoV-2 attack." (PMID 35720350, 2022).
tumor (continued). "In conclusion, the most important deduction of our work is that the protein concentration of ADAM17 was significantly higher in both tumor and margin in patients with CRC with coexisting DMT2 in comparison to CRC patients without DMT2." (PMID 36286024, 2022). "ADAM17 has been reported to induce local tumor invasion and metastasis via degrading the cell basement membrane and extracellular matrix and affecting tissue remodeling." (PMID 35720350, 2022). "They reported that the expression of ADAM17, which has been reported to release membrane-bound PD-L1, is high in tumor regions." (PMID 36140325, 2022). "It should also be noted that the activity of ADAM17 plays a crucial role in TNFR1-dependent tumor cell–induced endothelial cell death." (PMID 36591235, 2022). "The most important result of our work is that the protein concentration of ADAM17 in the tissue of both the CRC tumor and the surgical margin is higher in CRC patients with comorbidities such as DMT2 or CVD in comparison to CRC patients without these diseases." (PMID 36286024, 2022). "More than 90 substrates are regulated by ADAM17, some of which are closely relevant to tumor formation and development." (PMID 36466812, 2022). "The correlation of miR-365 with ADAM10 and ADAM17 expression in RB tumor samples appeared to be patient-dependent, but both ADAMs seem to be targeted by miR-365, at least in a subset of RB tumors." (PMID 36293469, 2022). "Different molecules, e.g., monoclonal antibodies, have been developed to inhibit ADAM proteins, rendering ADAM10 and ADAM17 potentially interesting targets in RB tumor therapy." (PMID 36293469, 2022). "Overall, most hydroxamate-based inhibitors exhibit potent ADAM17 shedding activity and resist tumor progression." (PMID 36466812, 2022). "The expression of ADAM17 in normal and tumor tissues was lower in the kidney and liver than in the heart." (PMID 35720350, 2022). "Our study sheds light on the interplay between cancer cells and their environment and in particular the role of ADAM17 controlling the cellular identity of tumor-resident macrophages and their function." (PMID 35998057, 2022). "ADAM17 was detected in a culture supernatant of cancer cell lines and primary tumor cultures as well as blood serum of cancer patients." (PMID 36293469, 2022). "Given the widespread overexpression of both ADAM17 and Tspan8 subfamily members in different tumor types, we assumed a functional interplay of these proteins in tumor cells." (PMID 36078095, 2022). "To validate the importance of ADAM17 as a tumor promoter in our in vitro models, we performed an experiment using a small interference RNA (siRNA) against ADAM17." (PMID 35216240, 2022). "A decreased ratio of PD-L1 protein to mRNA in the tumor is associated with poor prognosis and correlates with increased expression of ADAM10 and ADAM17 in a variety of malignancies." (PMID 34943606, 2021). "Inhibition of ADAM17-mediated CD16A shedding on NK cells by MEDI3622 was thereby shown to augment NK-cell stimulation via tumor targeting mAbs." (PMID 36860547, 2021). "Not surprisingly the supra-additive response to the combined treatment modality of RT and inhibition of ADAM17 on the in vivo level point towards multiple mechanisms of action, including tumor cell- and TME-oriented ionizing radiation-sensitive processes." (PMID 34055644, 2021). "It was previously demonstrated that ADAM17 contributed to tumor cell migration and invasion in vitro." (PMID 34746310, 2021). "ADAM17 can be activated by chemotherapeutics, which leads to enhanced tumor growth due to concomitant substrate cleavage." (PMID 33922533, 2021). "An ADAM17 inhibitor ZLDI-8 improved the anti-tumor activity of irinotecan in colon cancer cell lines acting in near-additive way and counteracting the induction of Notch1-4 expression by irinotecan." (PMID 34680255, 2021).
tumor (continued). "Several small molecular compounds were previously identified as ADAM17-specific inhibitors, which also induced an increased tumor response when combined with chemo- and radiotherapy." (PMID 36860547, 2021). "Factors shed by ADAM17 from NSCLC tumor cells (A549, H358) and relevant for endothelial cell migration were investigated using transwell migration assays, ELISA, and flow cytometry." (PMID 36860547, 2021). "In agreement with previous reports, we observed that expression levels of ADAM9, ADAM10, ADAM12 and ADAM17 were increased in tumor versus adjacent non tumor tissues except for ADAM10 that was non-significant, all were associated with poor prognosis." (PMID 33805340, 2021). "Here we investigate IR- and ADAM17-mediated intercellular communication between tumor and endothelial cells in vitro, and vessel formation with the angiogenesis-oriented chorio-allantoic membrane (CAM) assay ex ovo." (PMID 36860547, 2021). "Intriguingly, expression of ADAM17, which has been reported to release membrane-bound PD-L1, was high in both tumor regions and cell types." (PMID 33672843, 2021). "Since ADAM10 and ADAM17 mediate the cell surface cleavage of a large repertoire of substrates that can promote tumor growth, inhibition of their activities is expected to have general tumor inhibitory activities." (PMID 34572138, 2021). "Accumulating evidence suggested that ADAM17 was up-regulated in various cancers and was involved in tumor growth, invasion and metastasis." (PMID 34182543, 2021). "These endothelial migration–oriented results indicate an additional role of tumor cell–located ADAM17 toward the formation of a tumor vasculature." (PMID 36860547, 2021). "During metastasis formation, ADAM17 is required to trigger necrotic cell death in endothelial cells via TNF in order to allow the extravasation of tumor-derived cells." (PMID 34831323, 2021). "Our new results now indicate a multistep process in which irradiation initially increases expression and localization of VEGF at the plasma membrane as observed on the individual tumor cell level on ADAM17 inhibition." (PMID 36860547, 2021). "Subsequently, attempts were made to validate the applicability of ADAM17 as a tumor marker in the screening setting." (PMID 34771725, 2021). "ADAM17 was found to be highly expressed in various types of tumors as well as to affect tumor progression." (PMID 34650435, 2021). "It should be noted the recently developed new approach to inhibit ADAM17 in NK-cells using antibodies that enhance their anti-tumor activity." (PMID 34943606, 2021). "Exosomal ADAM17 upregulation and RNA interference in vivo and in vitro confirmed the function of exosomal ADAM17 as a tumor metastasis-promoting factor in CRC." (PMID 34650435, 2021). "It has also been shown that ADAM10 and ADAM17 cleave PD-L1 from the surface of tumor cells and extracellular vesicles." (PMID 34943606, 2021). "Numerous studies confirmed that ADAM17 plays a major role in modulating tumour growth and metastasis through regulating cell signalling pathways." (PMID 34362154, 2021). "Increased expression of many Adamalysins including ADAM8, ADAM9, ADAM10, ADAM12 and ADAM17 was reported in HCC and associated with tumor progression." (PMID 33805340, 2021). "With these data, we demonstrate new insights on the interaction between the tumor and the tumor vasculature and on the relevance of ADAM17 as a target for a combined treatment modality with radiotherapy." (PMID 36860547, 2021). "In vitro, VEGF was identified as the major factor responsible for IR-induced and ADAM17-dependent endothelial cell migration toward attracting tumor cells." (PMID 36860547, 2021). "We demonstrate that inhibition of the sheddase ADAM17 by the novel antibody MEDI3622 reduces IR-induced VEGF release from tumor cells relevant for endothelial cell migration and vasculature protection, thereby enhancing radiotherapy treatment outcome of NSCLC." (PMID 36860547, 2021).
tumor (continued). "Efficacy-oriented experiments were performed in a murine orthotopic NSCLC tumor model using irradiation with an image-guided small-animal radiotherapy platform alone and in combination with the novel ADAM17-directed antibody MEDI3622." (PMID 36860547, 2021). "All these factors were secreted in a similar RT-induced time- and dose-dependent manner from several NSCLC cell lines (and other tumor entities), indicative of a common upstream mechanism without changes at the transcriptional level, pointing towards ADAM17." (PMID 34055644, 2021). "Although, a putative IR-induced and ADAM17-dependent release of factors regulating tumor vasculature formation and integrity makes ADAM17 an interesting target for a combined treatment modality with radiotherapy." (PMID 36860547, 2021). "This is the first study proposing ADAM17 as a serum tumor marker in the setting of a gynecological tumor disease." (PMID 34771725, 2021). "In the present study, statistical analysis showed that the ADAM17 concentration was significantly lower when a macroscopic tumor residue remains (p = 0.048)." (PMID 34771725, 2021). "Similar to HUVECs, migration of HPMECs was also increased in response to IR, but only toward irradiated ADAM17-proficient tumor cells." (PMID 36860547, 2021). "ADAM family has been proved to be key regulators of cell signaling pathway in the tumor microenvironment and ADAM17 was widely involved in tumorigenesis and tumor progression." (PMID 34182543, 2021). "In further studies, it is conceivable to extend existing tumor markers by ADAM17 to allow more rapid early-stage detection." (PMID 34771725, 2021). "D1 (A12), a therapeutic monoclonal anti-ADAM17 antibody, was tested in a mice model of ovarian showed inhibition of tumor growth." (PMID 34912809, 2021). "A high ADAM17 concentration in serum at primary diagnosis is associated with early FIGO stages and predicts complete resection of the tumor mass." (PMID 34771725, 2021). "Other studies showed that autonomous TNF-α-NF-κB and IL-6-STAT3 signaling are essential for tumor growth while ADAM17 turn on the signaling cascade by the shedding of TNFα." (PMID 34182543, 2021). "Overall, ADAM17 is gaining recognition in the field of combined treatment modalities with RT, in particular for aggressive tumor entities with high recurrence rates." (PMID 34055644, 2021). "The relevance of tumor-derived VEGF is also demonstrated as part of our in vitro experiments with shRNA-downregulated ADAM17 activity and with the CAM assay." (PMID 36860547, 2021). "VEGF complementation to supernatants of ADAM17-inhibited, attracting tumor cells strongly indicate that VEGF is the major driving force for IR-induced endothelial migration." (PMID 36860547, 2021). "miR-152-induced tumor suppression effect was partially mediated by down-regulation of ADAM17 expression." (PMID 34182543, 2021). "In the last years, various in vitro investigations supplied more accurate knowledge on the molecular relationship between ADAM17 and iRhoms by the use of knockout mice in diverse inflammatory conditions and tumours." (PMID 34362154, 2021). "In contrast, inhibition of ADAM17 activity of irradiated tumor cells strongly abrogated IR-induced migration of HUVECs toward these MEDI3622-preincubated tumor cells." (PMID 36860547, 2021). "Our previous work demonstrated that ADAM17 is present on platelets (pADAM17) and contributes to immune evasion of metastasizing tumor cells." (PMID 34208863, 2021). "Actually, there are over 80 substrates cleaved by ADAM17, and many of them are involved in chronic inflammation, organ fibrosis and tumour progression." (PMID 34362154, 2021). "miR-122 reduced angiogenesis, inhibit intrahepatic metastasis and functioned as tumor suppressor through the regulation of ADAM17." (PMID 34182543, 2021).